B2M (beta-2-microglobulin)
Diseases named in the same sentence as B2M in open-access papers (continued):
Sharing a sentence is not in itself a finding about the gene and the disease.
ovarian carcinoma (continued). "Given that HRPT1 and B2M were expressed differently in the 50 specimens, which suggested that these two genes were not eligible reference genes, the combination of ACTB, RPLP0, PPIA, and TBP was recommended for use in epithelial ovarian cancer studies." (PMID 24776823, 2014). "Notably, OVA1® is a United States (US) Food and Drug Administration (FDA) approved test, which includes apolipoprotein A-I (APOA1), transthyretin (TTR), transferrin (TF), β2-microglobulin (B2M), along with MUC16, and has demonstrated effectiveness in detecting early-stage ovarian cancer." (PMID 40836974, 2024). "Recently, it is reported that B2M and 18S RNA are suitable internal reference genes in serum stimulated samples; GUSB and PPIA are believed to serve as internal reference genes in ovarian cancer, while RPL13A is identified to stably transcript in ovarian cancer cells treated with PTX and HCPT." (PMID 28184026, 2017).
Stroke (13 papers, 2010 to 2025). Sudden impairment of blood flow to a part of the brain due to occlusion or rupture of an artery to the brain. "As a trigger for the inflammatory process, B2M is related to atherosclerosis, which underlies the development of stroke." (PMID 37155257, 2023). "Our findings support the concept that B2M is related to stroke risk." (PMID 37155257, 2023). "Likewise, B2M is a sensitive biomarker for inflammatory conditions, infections, and cancer, and is positively associated with coronary heart disease, stroke, and mortality." (PMID 36650913, 2023). "Recent B2M change deserves consideration as a stroke and possibly a CHD risk marker." (PMID 24373343, 2013). "Notably, regardless of whether ischemic or hemorrhagic stroke, plasma B2M is an independent factor of early prognosis after the onset of stroke, and higher B2M levels is associated with a poorer early prognosis." (PMID 38743119, 2024). "Data from a clinical prospective cohort found that the baseline level of plasma B2M in stroke patients was notably higher compared to the normal control group." (PMID 38743119, 2024). "First of all, while a number of studies have observed a significant association between B2M and both inflammation and CVD, the role of B2M in stroke is still unclear." (PMID 37155257, 2023). "The use of B2M, cystatin C and LCN-2 as possible biomarkers allows the early identification of people with high stroke risk." (PMID 37155257, 2023). "Serum B2M, cystatin C and LCN-2 levels were significantly associated with stroke risk in the overall population (B2M: β = 0.595, p < .001; cystatin C: β = 3.718, p < .001; LCN-2: β = 0.564, p < .001) after adjustment for age." (PMID 37155257, 2023). "Serum B2M, cystatin C and LCN-2 are significantly associated with stroke risk and are potential novel clinical biomarkers in the assessment of stroke risk." (PMID 37155257, 2023). "In this population-based study of adults aged above 18 years, we confirmed that there is a significant association of serum B2M, cystatin C and LCN-2 levels with stroke risk in a general Chinese population, even after adjusting for age." (PMID 37155257, 2023). "We used ordinal regression to study the relationship between serum B2M, cystatin C, and LCN-2 with stroke risk in 1060 participants (mean age 45.4 ± 10.8 years, 46% male) from the Shenzhen-Hong Kong United Network on Cardiovascular Disease (SHUN-CVD) study." (PMID 37155257, 2023). "We aimed to investigate the relationship of B2M, cystatin C, and LCN-2 with stroke risk in a general Chinese population." (PMID 37155257, 2023). "We identified studies that reported associations of baseline serum or plasma B2M and CVD incidence, CVD mortality, or CHD and stroke separately, in either general populations or patients with renal disease." (PMID 33581388, 2021). "By all methods B2M expression was significantly increased in whole blood in the delayed phase of stroke and CD3E was significantly increased in CD4 cells." (PMID 25090612, 2014). "This work has also led to the identification of plasma B2M, IGFBP2, and especially IGFBP4 as novel risk markers for stroke risk among postmenopausal women." (PMID 24373343, 2013). "We previously reported positive associations of baseline B2M with CHD risk and baseline IGFBP4 with stroke risk during the first year from randomization in the WHI HT trials." (PMID 24373343, 2013). "The strongest associations in these analyses are for B2M and CHD and for IGFBP4 and stroke, while an inverse association of CHD risk with THBS1 and a positive association of stroke risk with IGFBP2 are also observed." (PMID 24373343, 2013). "B2M, THBS1, and CFD were confirmed (P <0.05) as novel CHD risk markers, and B2M, IGFBP2, and IGFBP4 were confirmed as novel stroke disease risk markers, while the assay for HPX proved to be unreliable." (PMID 24373343, 2013).
Stroke (continued). "This study confirms plasma B2M to be a risk marker for both CHD and stroke, over an average follow-up period of about 4 years for CHD, and longer for stroke." (PMID 24373343, 2013). "Although research on the role of B2M in ocular diseases is limited, neuroscience suggests that both B2M and LCN2 may serve as key biomarkers for assessing stroke risk and prognosis." (PMID 40083945, 2025). "Elevated serum B2M, cystatin C and LCN-2 levels are associated with stroke risk." (PMID 37155257, 2023). "Levels of B2M, cystatin C and LCN-2 among different strata of stroke risk factors." (PMID 37155257, 2023). "B2M, a component of MHC class 1 molecules, was also upregulated in infected cells and has been implicated as a risk marker for coronary heart disease and stroke." (PMID 36968839, 2023). "Since B2M levels correlate with CRP, TNF-α, IL-6, and cardiovascular risk factors in hemodialysis patients, this UT could possibly increase the risk of stroke by acting on inflammation." (PMID 30037144, 2018). "Plasma B2M is confirmed to be an informative risk marker for both CHD and stroke." (PMID 24373343, 2013). "These analyses also imply positive associations of stroke risk with IGFBP2, IGFBP4, and B2M." (PMID 24373343, 2013). "Our proteomic discovery work also suggests (P = 0.03) higher B2M levels in stroke cases versus controls, so that this marker may help to understand adverse effects of hormone therapy on cardiovascular disease more generally." (PMID 20667078, 2010). "We have identified B2M and IGFBP4 as novel risk markers for CHD and stroke, respectively." (PMID 20667078, 2010). "The associations of B2M with CHD (P < 0.001) and IGFBP4 with stroke (P = 0.005) were confirmed using ELISA in replication studies, and changes in these proteins following the initiation of hormone therapy use were shown to have potential to help explain hormone therapy effects on those diseases." (PMID 20667078, 2010). "In-depth proteomic discovery analysis of prediagnostic plasma samples identified B2M and IGFBP4 as risk markers for CHD and stroke respectively, and provided a number of candidate markers of disease risk and candidate mediators of hormone therapy effects on CHD and stroke." (PMID 20667078, 2010). "Beta-2-microglobulin (B2M) has been suggested as an emerging biomarker for cardiovascular diseases (CVD), including coronary heart disease (CHD) and stroke, and mortality." (PMID 33581388, 2021). "Fold change difference in the expression of B2M and CD3E in late phase stroke versus control subjects." (PMID 25090612, 2014). "Combined trial comparisons show CHD case-control differences (P <0.05) for B2M and CFD, and stroke case-control differences for B2M and IGFBP4." (PMID 24373343, 2013). "To more directly assess the role of B2M and IGFBP4 in mediating hormone therapy effects on CHD and stroke, respectively, we are currently carrying out ELISA analyses of baseline and 1-year plasma samples in the WHI hormone therapy trials." (PMID 20667078, 2010). "Therefore, the possibility that B2M-induced inhibition of neurogenesis may account for CKD-induced poor stroke recovery cannot be ruled out and should be investigated." (PMID 30037144, 2018). "Beta-2-microglobulin (B2M), cystatin C and lipocalin-2 (LCN-2) are established renal biomarkers, yet their roles in stroke have not been fully evaluated." (PMID 37155257, 2023).
Cognitive impairment (12 papers, 2017 to 2025). Abnormal cognition is characterized by deficits in thinking, reasoning, or remembering. "This study demonstrated the association of plasma B2M with CSF AD biomarkers as well as a possible important role of Aβ pathology in the association between B2M and cognitive impairment, particularly in cognitively normal individuals." (PMID 37005674, 2023). "Overall, the study identified an association between plasma B2M and CSF AD biomarkers and a possible important role of Aβ pathology in the association between B2M and cognitive impairment." (PMID 37005674, 2023). "Increased circulating levels of β2‐microglobulin (B2M), a component of major histocompatibility complex class 1, have been associated to aging phenomena, such as cognitive impairment and neurodegeneration." (PMID 36949664, 2023). "Among the genes expressed by microglia upon exposure to IFN-I we identified MHC-I-related B2m, and the complement component C4b19, 42, factors previously linked to cognitive impairment and ageing." (PMID 28959042, 2017). "Plasma B2M correlates with CSF biomarkers, including Aβ and tau proteins, which may play an important role in B2M’s association with cognitive impairment." (PMID 40837565, 2025). "It has also been shown in animal studies that B2M causes cognitive deficits in mice." (PMID 40837565, 2025). "In these proteins, elevated levels of Beta-2-Microglobulin (B2M) may cause neurological impairment resulting in cognitive deficits." (PMID 36959823, 2023). "Through parabiosis studies and plasma transfer experiments, elevated circulating B2M has been identified as a critical mediator of cognitive impairment in both DS patients and mouse models." (PMID 39985073, 2025). "Therapeutic interventions targeting peripheral B2M, including antibody neutralization and parabiotic circulation exchange, successfully reverse these cognitive deficits." (PMID 39985073, 2025). "Eliminating B2M in plasma represents a potential therapeutic strategy to partially reverse aging-related cognitive impairment." (PMID 38743119, 2024). "Previous studies have suggested a correlation between elevated levels of β2-microglobulin (B2M) and cognitive impairment." (PMID 37005674, 2023). "The evidence demonstrated the role of TLR4 in learning and memory function of Alzheimer’s disease (AD), we wondered if TLR4 affected B2M-induced cognition impairment." (PMID 32059688, 2020). "In this study, we found a pronounced increase of TLR4 expression in B2M-treated mice, which confirming a possible correlation with B2M-induced cognitive impairment." (PMID 32059688, 2020). "Collectively, these results suggest that the recovery of hippocampal autophagic flux is an important mechanism involved in H2S antagonizing B2M-induced cognitive defects." (PMID 31708756, 2019). "Taken together, these data also suggested that H2S reverses the cognitive impairment induced by B2M." (PMID 31708756, 2019). "It is confirmed that systemic or local administration of B2M into hippocampus impairs the function of learning and memory, and there is a possibility to reverse B2M-induced cognitive defects when the excessive B2M is removed." (PMID 31708756, 2019). "Our study concluded that B2M may be a risk factor for POD, which is consistent with the previous research linking B2M to cognitive impairment." (PMID 40837565, 2025). "In another clinical study involving a smaller sample size of 51 healthy individuals and 41 patients with age-related cognitive impairment, it was evident that the plasma B2M content in patients with cognitive impairment was markedly higher compared to that of the healthy controls." (PMID 38743119, 2024). "Moreover, a retrospective analysis involving 245 subjects (including 45 mild cognitive impairment patients, 100 healthy individuals, and 100 AD patients) revealed that plasma B2M levels was increased in AD patients compared to both normal controls and mild cognitive impairment (MCI) patients." (PMID 38743119, 2024).
Cognitive impairment (continued). "Therefore, we should further explore the association between serum and cerebral B2M concentration, and whether B2M deposits in the brain contributes to cognitive impairment based on human researches." (PMID 31643008, 2020). "B2M is the light chain of MHC-I, with regulatory effects on brain development and synaptic plasticity, and is thought to contribute to cognitive deficits." (PMID 40837565, 2025). "Experimental studies in AD mouse models have demonstrated that B2M reduction—achieved through genetic ablation, antisense oligonucleotide (ASO) administration, or antibody-based interventions—markedly attenuates cognitive deficits and reduces amyloid plaque burden." (PMID 39985073, 2025).
glioblastoma (12 papers, 2012 to 2025). The most malignant astrocytic tumor (WHO grade IV). "Thus, the new YT–Vav1+CISH–/– and YT–Vav1+B2M–/– modified NK cell lines demonstrate greater cytotoxic activity against primary patient’s glioblastoma spheroids compared with the standard line, causing early metabolic rearrangements and evident decrease of tumor cells viability." (PMID 40071076, 2025). "Incubation of human glioblastoma spheroids with YTVav1+ B2M–/– knockout NK cells also showed a 6-hour gradual increase of all fluorescence lifetime parameters." (PMID 40071076, 2025). "In this research, antitumor activity of YT-Vav1+CISH–/– and YT–Vav1+B2M–/– modified NK cell lines was evaluated using a model of 3D tumor spheroids of a patient’s glioblastoma." (PMID 40071076, 2025). "Within glioblastoma alone, for instance, two separate studies gathering single-cell RNA sequencing data from human tumors have found B2M expression to be inversely correlated with survival." (PMID 37537301, 2023). "According to the transcriptomic data from Ivy Glioblastoma Atlas Project, B2M was mainly enriched in hyperplastic blood vessels and microvascular proliferation." (PMID 33658560, 2021). "When performing our real-time RT-PCR assay on the glioblastoma samples, we used B2M as the reference gene." (PMID 22359620, 2012). "In addition, B2M signaling in glioblastoma cells activates the PI3K/AKT/MYC/TGFβ1 axis, which sustains cancer stem cell properties and promotes M2-like macrophage polarization." (PMID 40842996, 2025). "Glioblastoma cells and immune cells were identified based on the absence of EGFP and presence of B2M, respectively, as host feeder organoid cells are engineered to be EGFP-expressing and B2M-deficient." (PMID 39893177, 2025). "We noted an overlap of up-regulated genes with an immune signature reported in a glioblastoma profiling study, including MHC class I and II genes, the complement factors C1QA/B/C, FCGR3A, B2M, SOCS3, TLR2 and CTSH." (PMID 25593989, 2014). "The study used a primary culture of GBM7-Luc2-mKate2 human glioblastoma, a line of YT (YTwt) wildtype human NK cells, as well as lines created by us with overexpression of VAV1 protein with either CISH (YT–Vav1+CISH–/–) or B2M (YT–Vav1+B2M–/–) knockouts." (PMID 40071076, 2025).
leukemia (12 papers, 1984 to 2024). A malignant (clonal) hematologic disorder, involving hematopoietic stem cells and characterized by the presence of primitive or atypical myeloid or lymphoid cells in the bone marrow and the blood. "The data indicate that MLL-AF9 cells cannot grow well in the absence of MHC-I expression in WT and Rag2−/− mice, and it is likely that a small fraction of MLL-AF9 cells that escaped sgRNA-mediated B2m excision expand and predominate over B2m-deficient leukemia cells." (PMID 38129572, 2023). "The A1.4 mAb recognized B2m-free HLA HCs precipitated from the “W6/32-precleared SU leukemia cell lysate”." (PMID 39057057, 2024). "Transplanting the KMT2A-MLLT3 expressing cells into different immunodeficient mouse models led to AML in NSGS mice and AML, B-ALL or mixed lineage leukemia in NSG and NSG beta 2 microglobulin (NS-B2M) mice showing that the immune microenvironment plays an important role in leukemia development." (PMID 35756660, 2022). "In this work, we evaluated the use of human IGFBP2, B2M or Hsp90 as soluble markers of leukemia." (PMID 26068922, 2015). "With the exception of 3 leukaemias all were strongly beta 2 microglobulin+." (PMID 6201182, 1984). "For example, previous study found that B2M recognizes and activates T cell-mediated immune responses by stabilizing the expression of MHC I molecules on the cell surface, affecting their activity in the clearance of leukemia cells." (PMID 39422621, 2024). "We first assessed the in vitro cytotoxicity of expanded NK cells by co-culturing them with CD31+ ECs derived from H9-WT (A02/03B35/44DRB1+/+), HLA-edited (A02/−B35/−D−/−), and B2M knockout (B2M−/−DRB1−/−) hESCs, as well as with K562, a human leukemia cell line that lacks the HLA complex." (PMID 33423156, 2021).
autoimmune disease (11 papers, 2013 to 2025). A disorder resulting from loss of function or tissue destruction of an organ or multiple organs, arising from humoral or cellular immune responses of the individual to their own tissue constituents. "The high levels of serum and urinary B2M levels are associated with various hematologic malignancies, autoimmune diseases, and renal disorders." (PMID 39795957, 2024). "Beta-2-microglobulin is used in the diagnosis of active rheumatoid arthritis and kidney disease, and a structural variant of b2m has been associated with autoimmune disease and small-cell lung cancer." (PMID 24955979, 2014). "Beta-2-microglobulin, a marker of immune activation, has been implicated in various autoimmune diseases and could reflect chronic inflammation in this patient." (PMID 40007921, 2025). "This opens new avenues to immunotherapy of autoimmune diseases and even human cancers that express B2m-free HCs." (PMID 39057057, 2024). "B2M expression is often increased while immune system is stimulated, principally during infections, autoimmune diseases, or certain neoplasms." (PMID 38139297, 2023). "The B2M concentration is fairly constant in healthy individuals, whereas blood levels of B2M increase in disease states such as renal dysfunction and in certain malignancies, autoimmune diseases and infections." (PMID 36277688, 2022). "In addition, B2M expression is upregulated by infection or autoimmune disease." (PMID 23451040, 2013).